NBEA (neurobeachin)
Description:
Binds to type II regulatory subunits of protein kinase A and anchors/targets them to the membrane. May anchor the kinase to cytoskeletal and/or organelle-associated proteins (By similarity).
Synonyms: BCL8B; KIAA1544; LYST2; FLJ10197; NEDEGE
Tractability: Small molecule: it has a binding pocket of medium quality. Antibody: UniProt places it where antibodies can reach, with medium confidence; its Gene Ontology location is reachable by antibodies, with medium confidence. PROTAC: ubiquitination databases record sites on it; its protein half-life has been measured.
Gene: Protein-coding gene on chromosome 13 (34,942,270 to 35,673,022, forward strand). Ensembl gene ENSG00000172915.
Subcellular location: Cytoplasm; Membrane
Subcellular location (Human Protein Atlas): Golgi apparatus; Cytosol
Pathways (Reactome):
Neuronal System: Assembly and cell surface presentation of NMDA receptors; Neurotransmitter receptors and postsynaptic signal transmission
Signal Transduction: NOTCH1 Intracellular Domain Regulates Transcription; PKA activation
Gene Ontology:
Molecular function: protein kinase binding
Biological process: synapse organization
Cellular component: cytosol; endomembrane system; membrane; plasma membrane; trans-Golgi network; cytoplasm
Genetic constraint (gnomAD): Loss-of-function variants: 21 observed, 220.8 expected, observed/expected ratio (o/e) 0.0951, 90% interval 0.066 to 0.14. The upper end of that interval is the gene's LOEUF score, 0.14, which puts it in group 1 of 6, group 1 being the genes least tolerant of losing a copy. Missense variants: 2,064 observed, 2,864.4 expected, observed/expected ratio (o/e) 0.72, 90% interval 0.69 to 0.75. Synonymous variants: 928 observed, 984.06 expected, observed/expected ratio (o/e) 0.94, 90% interval 0.89 to 1.
Gene-disease validity (ClinGen):
ClinGen rates the evidence that NBEA causes each of these diseases.
complex neurodevelopmental disorder (autosomal dominant): Definitive. A disorder that involves more than one phenotype associated with the central nervous system, including but not limited to intellectual disability, autism, and seizures (epilepsy).
Homologues: Orthologues: chimpanzee NBEA (99% identical), macaque NBEA (99% identical), pig NBEA (99% identical), rat Nbea (97% identical), mouse Nbea (97% identical), rabbit NBEA (94% identical), guinea pig NBEA (93% identical), tropical clawed frog nbeal3 (90% identical), zebrafish nbeaa (85% identical), zebrafish nbeab (79% identical), Caenorhabditis elegans sel-2 (37% identical), dog NBEA (25% identical), and 1 more. Paralogues in human: LRBA (62% identical), NBEAL1 (18% identical), NBEAL2 (18% identical), WDFY4 (16% identical), WDFY3 (16% identical), LYST (15% identical), NSMAF (9% identical).
Diseases named in the same sentence as NBEA in open-access papers:
NBEA is named in the same sentence as 25 diseases in open-access papers, as found by Europe PMC text mining. Sharing a sentence is not in itself a finding about the gene and the disease. The quoted sentences say what the papers report.
autism (19 papers, 2010 to 2023). Persistent deficits in social interaction and communication and interaction as well as a markedly restricted repertoire of activity and interest as well as repetitive patterns of behavior. "Disruption of the Neurobeachin gene is a rare genetic mutation that has been implicated in the development of autism and enhanced long-term potentiation of the hippocampal CA1 region, causing a heightened conditioned fear response and impaired fear extinction." (PMID 34949210, 2021). "Intriguingly, we previously found that the autism associated gene neurobeachin, which encodes a scaffolding protein thought to act within the trans-Golgi network, was required postsynaptically for electrical synaptogenesis." (PMID 28530549, 2017). "A single nucleotide polymorphism (SNP) of neurobeachin gene has also been found to associate with autisms." (PMID 25647412, 2015). "It is intriguing that heterozygous perturbations of the NBEA gene have been linked to three dissimilar medical conditions: autism, multiple myeloma, and now obesity." (PMID 22438821, 2012). "Although mutations in genes encoding neurobeachin have been shown in autism patients, the consistent idea on the molecular pathogenesis of autisms is still unknown." (PMID 25647412, 2015). "The human homolog of rg, NBEA, has been implicated in myeloma and autism." (PMID 22496853, 2012). "The association of heterozygous human NBEA mutations with autism and cancer suggested that NBEA haploinsufficiency may produce related phenotypes in mice, and we therefore investigated Nbea+/− mice in the phenotyping screen of the German Mouse Clinic (GMC)." (PMID 22438821, 2012). "These Ca2+-independent full fusions require PKA-R2, a PKA phosphorylation site on Complexin and the acute presynaptic function of Rugose, the homolog of mammalian neurobeachin, a PKA-R2 anchor implicated in learning and autism." (PMID 37303204, 2023). "Similar to our finding, the coincidence of potentiated LTP and impaired spatial learning and memory has been reported in the autism candidate molecule, neurobeachin (Nbea) haploinsufficient (Nbea + /−) mice." (PMID 37268701, 2023). "Further, a de novo breakpoint in the neurobeachin (NBEA) gene on chromosome 13q was identified in a male patient with autism." (PMID 35204682, 2022). "Deletion of the autism candidate molecule neurobeachin (Nbea), a large PH-BEACH-domain containing neuronal protein, has been shown to affect synaptic function by interfering with neurotransmitter receptor targeting and dendritic spine formation." (PMID 32994505, 2020). "Heterozygous NBEA (Neurobeachin) gene rearrangements have been detected in groups of patients with either autism or monoclonal gammopathy and multiple myeloma." (PMID 28814779, 2017). "A brain-enriched multi-domain scaffolding protein, neurobeachin has been identified as a candidate gene for autism patients." (PMID 25647412, 2015). "The common sweep region on BTA12 contains neurobeachin (NBEA) and mab21-like 1 (MAB21L1) which have been implicated in human autism and psychiatric disorders, respectively." (PMID 23758707, 2013). "A de novo translocation in the NBEA gene was detected in an autistic patient, and additional evidence linking deletions of the chromosomal region containing NBEA to autism has been found (; OMIM 608049)." (PMID 22438821, 2012). "While some studies have reported positive findings on chromosome 13 for autism, attention has focused on the neurobeachin gene (NBEAL2), which lies in between our two regions and is, therefore, not supported by our data." (PMID 20678250, 2010). "In addition, NBEA is specifically expressed in sub-brain regions including excitatory neurons (ExDp1, ExDp2, ExM, and ExM-U) and interneurons (InMGE), suggesting a link between these sub-brain regions and autism." (PMID 36791193, 2023). "We identified Neurobeachin (NBEA), an autism-related regulator of synaptic protein trafficking, to be upregulated after contextual fear memory retrieval." (PMID 30213954, 2018).
autism spectrum disorder (5 papers, 2013 to 2021). A spectrum of developmental disorders that includes autism, and Asperger syndrome. "NEUROBEACHIN (NBEA) has previously been identified as a candidate gene for autism spectrum disorder (ASD) based on associations and linkage studies and patients with monoallelic inactivation of NBEA." (PMID 25333629, 2014). "Neurobeachin (NBEA) has been identified as a candidate gene for autism spectrum disorders (ASD) in several unrelated patients with alterations in the NBEA gene." (PMID 24188528, 2013). "Neurobeachin (NBEA) is an autism spectrum disorders (ASD) candidate gene." (PMID 26999814, 2016).
developmental delay (2 papers, 2021 to 2023). "The region contains 36 genes including NBEA, which emerged as the candidate gene associated with developmental delay." (PMID 34573300, 2021).
breast carcinoma (1 paper, 2017). "Similarly, miR-7641 inhibition in MDA-MB-231 breast cancer cells upregulated RPS16, TNFSF10, MSRB3, CDNF, ZNF616, and NBEA, downregulated CUL3, and showed no remarkable changes for PIGC and the other genes." (PMID 28827731, 2017).
sarcoma (1 paper, 2017). A usually aggressive malignant neoplasm of the soft tissue or bone. "Moreover, the detection by RT-PCR of specific sarcoma genes like ARSG,MYLK, and NBEA confirmed our assumption, even though the level of expression of ARSGand MYLK were lower than that of mouse sarcoma WEHI-164 cell line used as positivecontrol." (PMID 28430664, 2017).
serous ovarian cancer (1 paper, 2021). "Additionally, higher expression of NBEA was associated with worse OS in the early stages of serous ovarian cancer." (PMID 34577856, 2021). "This showed that higher expressions of CDCA3, CENPF, NCAPG, RRM2, UBE2C, and NBEA were associated with worse OS regardless of serous ovarian cancer stages." (PMID 34577856, 2021).
cancer (7 papers, 2012 to 2026). A tumor composed of atypical neoplastic, often pleomorphic cells that invade other tissues. "Twelve genes were located in eight of the top-15 breakpoint regions, and six of these genes are associated with cancer (CACNA1B, IBSP, MEPE, NBEA, RELN and THSD7A)." (PMID 31249626, 2019). "NBEA has been identified as a novel tumor suppressor gene, and the pathogenesis of IPF shares similarities with cancer, particularly in genetic expression, signaling pathways, and cellular senescence." (PMID 41481554, 2026). "We also investigated four genes, RAI2, KCNMA1, NBEA, and KIT, in the two ranking lists, and their potential functions for these two types of cancer." (PMID 31888440, 2019). "While three of the chimeras (ACTB->POTEM, ACTB->POTEE and SP100->HMGB1) have been found in normal population, three of the chimeras (C2orf27A->NBEA, HILPDA->EFCAB3, FARSB->TRIM61) were previously identified only in cancer samples." (PMID 25133550, 2014).
tumor (4 papers, 2019 to 2025). "Interestingly, only C8orf33 and NBEA seemed to have tumor suppressor functions." (PMID 31249626, 2019). "This suggests that its targets, such as SH3BP5, NBEA, ZBTB20, ESR2, and ESR1, may escape miR-204-mediated repression, potentially leading to their overexpression, which could promote tumor growth and metastasis." (PMID 41009685, 2025).
neurodevelopmental disorder (3 papers, 2020 to 2021). A behavioral and cognitive disorder with onset during the developmental period that involves impaired or aberrant development of intellectual, motor, or social functions. "Whereas there is currently no study on the synaptic vesicle glycoprotein 2B in insects, neurobeachin was associated in D. melanogaster to neurodevelopmental disorders, disruption of synaptic properties and impaired behavior or associative learning." (PMID 33670203, 2021). "Indeed, mutations in NBEA have been identified in ASD and neurodevelopmental disorders." (PMID 33133139, 2020).
neurological disease (3 papers, 2016 to 2023). "Five known PKA substrates (FLNA, ACTB, SOX9, MAP4K1 and GBF1) interacted with the domain modules of NBEA and three of these are linked with neurological disorders (FLNA, ACTB, SOX9)." (PMID 26999814, 2016). "SFN is located at the center of an interaction network of proteins including HYAL2, NBEA, NBR1, AURKAIP1, RALGPS2, and SLC1A2, some of which have known involvement in brain function and neurological disease." (PMID 31029150, 2019).
NBEA also shares sentences with these, for which no sentence is quoted: multiple myeloma (4 papers); epilepsy (3); Cyanosis (1); diabetes mellitus type 2 (1); embryonal rhabdomyosarcoma (1); Epileptic encephalopathy (1); gastric cancer (1); hemorrhage (1); Intellectual disability (1); monoclonal gammopathy (1); Obesity (1); ovarian carcinoma (1); ovarian teratoma (1); psychiatric disorder (1); schizophrenia (1).